ITGA6 (integrin subunit alpha 6)
Diseases named in the same sentence as ITGA6 in open-access papers (continued):
Sharing a sentence is not in itself a finding about the gene and the disease.
infection (12 papers, 2010 to 2025). The state of being infected such as from the introduction of a foreign agent such as serum, vaccine, antigenic substance or organism. "In particular, Itga6 expression has been related to focal adhesion involved in the immune response of Cynoglossus semilaevis to the infection of Vibrio vulnificus." (PMID 39062828, 2024). "B cell transcriptomics indicated significant downregulation of several adhesion molecules during infection, including S1PR1, S1PR2, ITGA4, ITGA6, GPR183, and CCR7." (PMID 37146079, 2023). "At 48 h after seeding (45 h post infection) cells were fixed and FACS sorted using the basal cell markers p63 and ITGA6 together with GFP as a marker of infected cells." (PMID 25033192, 2014). "In THP-1 cells, ITGA6 is induced at 96 h post-infection in the absence of pUS2/TRC8-mediated degradation, suggesting an antiviral role in this cellular context and/or stage of infection." (PMID 38687323, 2024).
adenocarcinoma (5 papers, 2013 to 2021). A common cancer characterized by the presence of malignant glandular cells. "In our TNBC model, we found up-regulation of Pou5F1 (Oct-3/4), Kit, Cd24 and Itga6 (Cd49f) in epithelial-like adenocarcinoma areas of primary tumors, while Klf4, Sox2, Cripto-1 were expressed in the mesenchymal/EMT-like regions." (PMID 26059540, 2015). "In addition, ITGAV was significantly over-expressed in tumors showing perineural invasion (P < 0.05), and ITGA5 and ITGA6 were significantly over-expressed in mucinous-type tumors compared with adenocarcinoma (P < 0.05)." (PMID 23705994, 2013). "These TOs showed budding acinar and adenocarcinoma-like architectures, with dominant expression of luminal markers (CK8, PSA, and AR) and less abundant expression of basal markers (CD49f/ITGA6, KRT5, KRT6)." (PMID 34884926, 2021).
genetic disorder (1 paper, 2023). "EB-PA is a rare genetic disorder characterized by increased skin fragility and PA involving mutations in the ITGB4, PLEC, or ITGA6 genes." (PMID 37033187, 2023).
ITGA6 also shares sentences with these, for which no sentence is quoted: prostate tumors (7 papers); triple-negative breast carcinoma (7); colorectal (3); invasive breast carcinoma (3); squamous cell carcinoma (3); asthma (2); bladder tumor (2); diabetes (2); immune system diseases (2); lupus- (2); lymphoma (2); metastatic disease (2); neurological disorders (2); non-small cell lung carcinoma (2); ovarian tumor (2); pancreatic adenocarcinoma (2); skin disorder (2); anaplastic thyroid carcinoma (1); autism (1); autoimmune disease (1); Autoimmunity (1); Azoospermia (1); basal cell carcinoma (1); benign prostatic hyperplasia (1); brain tumors (1); B‐cell precursor acute lymphoblastic leukemia (1); Cachexia (1); cardiac hypertrophy (1); cardiomyopathy (1); cervical intraepithelial neoplasia (1).
A further 48 diseases each share a sentence with ITGA6 in 1 paper.